RPS6KA3 (ribosomal protein S6 kinase A3)
Diseases named in the same sentence as RPS6KA3 in open-access papers:
RPS6KA3 is named in the same sentence as 104 diseases in open-access papers, as found by Europe PMC text mining. Sharing a sentence is not in itself a finding about the gene and the disease. The quoted sentences say what the papers report.
Coffin-Lowry syndrome (47 papers, 2006 to 2026). "Background/Objectives: Coffin-Lowry syndrome (CLS) is a rare X-linked disease caused by pathogenic variants in the RPS6KA3 gene." (PMID 41975704, 2026). "Heterogeneous loss-of-function mutations of the human RSK2 gene (RPS6KA3) have been implicated in Coffin–Lowry syndrome, which is characterized by multiple symptoms including growth retardation and cognitive impairment." (PMID 36806093, 2023). "At the molecular level, Coffin–Lowry syndrome is caused by loss-of-function mutations in RSK2 (also known as RPS6KA3), which encodes a serine/threonine protein kinase in humans." (PMID 37107631, 2023). "A novel hemizygous missense variant, c.1606G>T (p.V536F), in RPS6KA3 was identified in a patient with Coffin–Lowry syndrome." (PMID 34217350, 2021). "Coffin–Lowry syndrome is caused by mutations in the RSK2 (RPS6KA3) gene located at Xp22.2, which codes a member of the ribosomal S6 protein kinase family." (PMID 34439726, 2021). "Variants in ribosomal protein S6 kinase A3 (RPS6KA3) cause Coffin-Lowry syndrome (CLS) with variable phenotypes, e.g., with digital and facial anomalies as well as syndromic intellectual disability." (PMID 32951567, 2021). "Coffin–Lowry syndrome is an example of XLID that arises as a result of X-linked dominant inheritance of mutated RPS6KA3 (ribosomal protein S6 kinase, 90 kDa polypeptide 3) on the X chromosome." (PMID 23596395, 2013). "Coffin-Lowry syndrome (MIM ID# 303600) is caused by mutations in RPS6KA3 on chromosome Xp22.12, and is characterized by skeletal malformation, growth retardation, cognitive impairments, hearing deficit, and paroxysmal movement disorders." (PMID 23227143, 2012). "Mutations in RPS6KA3 are responsible for the Coffin-Lowry Syndrome and GDI1 has been related to nonsyndromic MR forms." (PMID 18047645, 2007). "Although reported to be overexpressed in various cancers, the role of Rsk2 in bone was primarily uncovered by the genetic examination of patients with Coffin–Lowry syndrome, an X-linked disease caused by loss-of-function variants in RPS6KA3, the gene encoding Rsk2." (PMID 40634321, 2025). "Mutation of RPS6KA3 can induce Coffin-Lowry syndrome, an X-linked syndrome." (PMID 30740391, 2019). "Coffin-Lowry syndrome (CLS) is caused by mutation in the RSK2 gene (RPS6KA3) on chromosome Xp22.12." (PMID 29311971, 2017). "Most of the research on Rps6ka3 pertains to Coffin-Lowry syndrome, and currently, there are no reports of its association with cataracts." (PMID 39883715, 2025). "Loss-of function mutations in the RPS6KA3 gene, which encodes the RSK2 protein, have been implicated in Coffin-Lowry Syndrome (CLS), an X-linked mental retardation disorder associated with cognitive deficits and behavioral impairments." (PMID 24086335, 2013).
melanoma (19 papers, 2013 to 2025). A malignant, usually aggressive tumor composed of atypical, neoplastic melanocytes. "The results indicated that RPS6KA3/RSK2 has the highest expression abundance in melanoma cells." (PMID 39424777, 2024).
breast carcinoma (16 papers, 2008 to 2025). "A study by Guo and Kong (2021) revealed that RPS6KA3 plays a significant role in breast cancer proliferation, migration, and invasion." (PMID 37664112, 2023).
Intellectual disability (13 papers, 2007 to 2026). "Coffin–Lowry syndrome (CLS) is a rare X-linked disorder caused by pathogenic variants in RPS6KA3, presenting with intellectual disability, distinctive facial and skeletal features, and variable systemic involvement." (PMID 41589305, 2025). "AFF2, DOCK8, NIPBL, and RPS6KA3 were implicated in intellectual disability." (PMID 23227143, 2012). "As previously pointed out we propose that the copy number alteration of dosage sensitive genes RPS6KA3 and GDI1 may be the major cause for the mental retardation in cases 4 and 6, respectively." (PMID 18047645, 2007). "Loss of function variants in SH3KBP1 are most commonly detected in patients with IMD61, but findings on two families with intellectual disability and large duplications encompassing SH3KBP1, EIF1AX, and RPS6KA3 genes indicate a possible role for SH3KBP1 in addition to that of RPS6KA3." (PMID 37510394, 2023).
osteosarcoma (8 papers, 2016 to 2025). A usually aggressive malignant bone-forming mesenchymal neoplasm, predominantly affecting adolescents and young adults. "LINC00665-drived polypeptide has tumor-suppressor features in osteosarcoma cells through repression of motility and proliferation by distracting the interaction of CREB1 and RPS6KA3." (PMID 38351332, 2024).
liver cancer (6 papers, 2014 to 2024). An epithelial or non-epithelial malignant neoplasm that arises from the liver. "Similarly, mutations perturbing the ATP binding pocket of the RPS6KA3 kinase are associated to a significant increased risk in liver cancers (Cox, p = 8.65e−4) as well as cross-cancer (p = 3.71e−2)." (PMID 27698488, 2016). "Moreover, the liver cancer-related driver genes RPS6KA3 and DYNC2H1 and the tumor migration-related gene CDH9 were also significantly different between the two groups." (PMID 37409259, 2023). "Thus, HNF4A is likely to be a novel driver gene for liver cancer, as well as ARID2 and RPS6KA3." (PMID 25526364, 2014).
Cognitive impairment (4 papers, 2007 to 2023). Abnormal cognition is characterized by deficits in thinking, reasoning, or remembering. "The detection in our series of two cases with smaller duplications involving GDI1 and RPS6KA3 genes reinforces the idea that increased gene dosage of these genes may be related to abnormal cognitive impairment." (PMID 18047645, 2007).
hepatocellular carcinoma (4 papers, 2014 to 2025). A malignant tumor that arises from hepatocytes. "Conversely, premature termination mutations in RPS6KA3, (and hence reductions in its amount), have been associated with the development of hepatocellular carcinomas." (PMID 25222612, 2014). "Through transcriptome sequencing of human hepatocellular carcinoma (HCC) samples, six genes—TSC1, TSC2, PABPC3, HIF1α, RB1CC1 (ATG17), and RPS6KA3 (RSK2)—were found to be associated with HBV infection." (PMID 33059752, 2020).
epilepsy (3 papers, 2018 to 2025). A brain disorder characterized by episodes of abnormally increased neuronal discharge resulting in transient episodes of sensory or motor neurological dysfunction, or psychic dysfunction. "This study identified 15 key genes linked to epilepsy, such as RPS6KA3 and TNFRSF1A, which are involved in lipid metabolism, apoptosis, and inflammation." (PMID 40520613, 2025). "The complex regulatory associations between genes such as RPS6KA3 and MAP2K4 and multiple miRNAs highlight that these miRNAs may play essential roles in the pathological process of epilepsy by regulating gene expression." (PMID 40520613, 2025). "Fifteen potential key genes in epilepsy were identified, including RPS6KA3, CTSD, and NCAM1." (PMID 40520613, 2025). "Among the triplosensitive genes located in the duplicated region, ARX, CDKL5, CNKSR2, MID1, PTCHD1, RPS6KA3, and SMS are known to be involved in intellectual developmental disorders with/without epilepsy." (PMID 39062680, 2024).
Obesity (2 papers, 2015 to 2024). Accumulation of substantial excess body fat. "Of note, mice deficient in EIF2AK4 exhibit resistance to obesity and hepatic steatosis induced by high fat diet and streptozotocin-induced diabetes is associated with elevated abundance and activity of RPS6KA3 in skeletal muscle." (PMID 39446839, 2024).
prostate carcinoma (2 papers, 2012 to 2023). A carcinoma that arises from epithelial cells of the prostate gland. "Ribosomal protein S6 kinase (RPS6KA3), which has been implicated in regulating AR activity and prostate cancer cell growth, was identified in this screen, supporting an RNAi screening approach to identify kinases regulating prostate cancer cell growth." (PMID 22761715, 2012). "The screen identified kinases previously shown to regulate prostate cancer cell growth and AR activity, including the ribosomal S6 kinase (RPS6KA3 or RSK)." (PMID 22761715, 2012).
estrogen-receptor negative breast cancer (1 paper, 2015). "Large screening efforts using small interfering RNAs identified RPS6KA3 (encoding RSK2) as being absolutely required to sustain the growth of estrogen-receptor negative breast cancer suggesting it may be a relevant target." (PMID 26011941, 2015).
papilloma (1 paper, 2023). A benign epithelial neoplasm that projects above the surrounding epithelial surface and consists of villous or arborescent outgrowths of fibrovascular stroma. "We further found that higher expression of HRAS was positively correlated with higher phosphorylation of MAP3K1, MAPK1, and RPS6KA3, and the expression of RPS6KA3 was higher in papilloma than PUC." (PMID 37704624, 2023).
schwannoma (1 paper, 2021). A benign, usually encapsulated slow growing tumor composed of Schwann cells. "Similarly, the non-RTK PTK2/FAK and the serine-threonine kinases GAK, RPS6KA3/RSK2, and MARK3 were also found to be greatly suppressed in brigatinib-treated schwannoma cells." (PMID 34264955, 2021).
X-linked deafness (1 paper, 2024). "First, some X-linked deafness genes were not included in the predefined panel containing 227 HL-related genes, such as RPS6KA3, EFNB1, HDAC8, ARX, and ANOS1, which may cause a negative molecular diagnosis for some patients." (PMID 39272213, 2024).
X-linked disease (1 paper, 2020). X-linked form of disease. "CLS represents an X-linked disease, caused by loss-of-function mutations in the gene RPS6KA3 encoding for the growth-factor-regulated protein kinase RSK2, which phosphorylates activating transcription factor 4 (ATF4, also called CREB-2)." (PMID 32668736, 2020).
cancer (69 papers, 2008 to 2025). A tumor composed of atypical neoplastic, often pleomorphic cells that invade other tissues. "Our data analysis also showed that miR-98 and miR-205 have two common predicted target genes FZD3 and RPS6KA3, which are actually genes associated with carcinoma according to the Online Mendelian Inheritance in Man (OMIM) database." (PMID 25521201, 2014). "On the other hand, RPS6KA3, identified as one of the top 10 cancer driver targets in the uPAR translational networking, belongs to a family called ribosomal S6 kinases (RSKs)." (PMID 37895906, 2023). "The next question we asked ourselves was, how relevant WNK3 and the other four top inhibited targets (EIF2AK2, p38γ, PAK1, and RPS6KA3) are to cancer." (PMID 35163434, 2022). "In this study, we discovered that RIPK2 interacts with six protein kinases: MKK7 (MAP2K7), DNA-PKcs (PRKDC), RSK2 (RPS6KA3), MST4 (STK26), MEK2 (MAP2K2), and CSK (CSK), many of which were implicated in cancer metastasis." (PMID 35115556, 2022). "Five of these genes, PTEN, TSC2, RPS6KA3, MYCN and Myo5A, form a connected module (module 9) associated with cancer biology." (PMID 24204314, 2013). "Within the down-regulated signaling pathways, there were ubiquitin-mediated proteolysis, mTOR signaling, pathways in cancer, RIG-like receptor signaling pathway with Herc1 and Traf6, Mapk1 and Rps6ka3, Ifg1r, Prkx, and Foxo1 as the core regulatory factors." (PMID 26900402, 2016).
tumor (63 papers, 2008 to 2025). "Molecular analysis of the HCC-like component of the tumor, demonstrated a highly unstable hyperdiploid genome and evidence of altered cell cycle control, possibly associated with the MDM4 copy gain (located in 1q32), as well as MAPK signaling pathway activation resulting from the RPS6KA3 variant." (PMID 37903123, 2024). "It hinders cAMP response element binding protein 1 (CREB1) binding to ribosomal protein S6 kinase A3 (RPS6KA3), thereby inhibiting tumor growth." (PMID 41181701, 2025). "To address the first question, we correlated the microarray-based mRNA expression of the 5 CSA targets (EIF2AK3, MAPK12/p38γ, PAK1, RPS6KA3, and WNK3) in a panel of 60 tumor lines of the NCI, USA, with 83 standard anticancer agents." (PMID 35163434, 2022). "The kinases MAPKAPK2, RPS6KB1 and RPS6KA3 were more often regulated in the noncancer conditions when compared to their degree of regulation in tumours." (PMID 36688815, 2023). "In addition, the phosphorylation of the RPS6KA3 substrates (BAD S118, MTOR S1261, SRF S224, etc.), which involved in the regulation of cell differentiation and the inhibition of apoptotic were upregulated in tumor samples." (PMID 37704624, 2023).
infection (7 papers, 2014 to 2025). The state of being infected such as from the introduction of a foreign agent such as serum, vaccine, antigenic substance or organism. "Comparing the most modulated genes between activated and non-activated cells at 24h post-infection, we observed that SETDB2 and RPS6KA3 were up-regulated in both conditions, however in activated cells the modulation occurred to a greater extent." (PMID 25875202, 2015).
neurological disease (3 papers, 2007 to 2024).
RPS6KA3 also shares sentences with these, for which no sentence is quoted: myeloma (12 papers); glioblastoma (8); multiple myeloma (7); skin cancer (7); acute myeloid leukemia (6); colon cancer (6); gastric cancer (5); glioma (5); lung carcinoma (5); ovarian carcinoma (5); triple-negative breast carcinoma (5); head and neck squamous cell carcinoma (4); colorectal cancer (3); Osteopenia (3); squamous cell carcinoma (3); Breast Tumor (2); cervical carcinoma (2); gastric tumor (2); genetic disease (2); heart failure (2); mantle cell lymphoma (2); metastatic disease (2); pancreatic adenocarcinoma (2); pancreatic cancer (2); rheumatoid arthritis (2); viral infection (2); Arthritis (1); Barth syndrome (1); basal cell carcinoma (1); bone tumor (1).
A further 54 diseases each share a sentence with RPS6KA3 in 1 paper.